NEK1 (NIMA related kinase 1)
Diseases named in the same sentence as NEK1 in open-access papers (continued):
Sharing a sentence is not in itself a finding about the gene and the disease.
Cognitive impairment (3 papers, 2020 to 2022). Abnormal cognition is characterized by deficits in thinking, reasoning, or remembering. "Two mismatch cases had an underlying genetic mutation, both of which were a C9orf72 hexanucleotide repeat expansion (30%), compared to five genetic mutations (four C9orf72 and one NEK1 mutation) in the 11 comparison cases with cognitive deficits (45%)." (PMID 31386770, 2020). "Intriguingly, none of the patients with ALS carrying NEK1 LoF variants described up to date had cognitive impairment, except for one case, whereas C9orf72 association to ALS-FTD is well known." (PMID 35495032, 2022). "In our study, none of the NEK1 LoF carriers had cognitive impairment; moreover, we found three patients carrying a NEK1 likely benign missense variant that presented also with FTD, but all of them carried also the C9orf72 expansion." (PMID 35495032, 2022).
frontotemporal dementia (3 papers, 2019 to 2025). Frontotemporal dementia (FTD) comprises a group of neurodegenerative disorders, characterized by progressive changes in behavior, executive dysfunction and language impairment, as a result of degeneration of the medial prefrontal and frontoinsular cortices. "Mutations in the NEK1 gene have been associated with a variety of disorders, including short-rib polydactyly syndrome, axial spondylometaphyseal dysplasia (SMD), frontotemporal dementia (FTD) with ALS, and ALS." (PMID 40282367, 2025).
Joubert syndrome (3 papers, 2013 to 2025). Joubert syndrome (JS) is characterized by congenital malformation of the brainstem and agenesis or hypoplasia of the cerebellar vermis leading to an abnormal respiratory pattern, nystagmus, hypotonia, ataxia, and delay in achieving motor milestones. "For instance, mutations in NEK1 have been linked to HSP, cerebellar ataxias, and the rare genetic disorders, Joubert syndrome and Meckel-Gruber syndrome." (PMID 41154634, 2025). "Inherited or acquired dysfunction of NEKs also disrupts ciliary and centrosomal homeostasis, as seen in PKD and Joubert syndrome, and compromises neuronal viability, as exemplified by ALS- and PD-associated NEK1 variants." (PMID 41154634, 2025).
lymph node metastasis (3 papers, 2020). "High expression of NEK1 was also observed in tumors with multifocality and in patients with lymph node metastasis, associating NEK1 with a poor prognosis." (PMID 32294979, 2020). "Nek1 expression was elevated in thyroid tumors with multifocality and in patients with lymph node metastasis." (PMID 32429458, 2020). "In the present work, we demonstrate that the expression of NEK1 might be used as a predictive factor for lymph node metastasis in patients with DTC (Differentiated thyroid cancer)." (PMID 31906878, 2020).
lymphoma (3 papers, 2011 to 2023). A malignant (clonal) proliferation of B- lymphocytes or T- lymphocytes which involves the lymph nodes, bone marrow and/or extranodal sites. "In kat2J mice with only one normal allele of NEK1, we observed an important consequence of defective DNA damage repair and chromosome instability: a very high incidence of tumors, in particular lymphomas." (PMID 21214959, 2011). "NEK1 deficiency and the chromosome instability associated with it also have consequences in vivo: NEK1 heterozygous mice develop lymphomas with a much higher incidence than wild type littermates." (PMID 21214959, 2011). "NEK1 also seems to function as a tumor suppressor, since mice heterozygous for a NEK1/kat2J mutation develop tumors, specifically lymphomas, with a much higher incidence compared to their wild type littermates." (PMID 21214959, 2011). "NEK1 null mice also developed lymphomas, but most of them died at early ages from other causes." (PMID 21214959, 2011). "Importantly, lymphoma cells were devoid of Nek1 immunoreactivity, suggestive of loss of heterozygosity at this locus." (PMID 22040655, 2011). "Nek1-null mice seem to be in important ways similar to Atm-deficient mice and humans with ataxia-telangiectasia, which survive embryonic and early adult stages, but which age prematurely and develop lymphomas and other tumors later in life as they're exposed to environmental insults." (PMID 21214959, 2011). "NEK1 knockout mice result in the failure of cell cycle checkpoint arrest in response to DNA damage, resulting in genomic instability and lymphoma development." (PMID 37046733, 2023). "In the few NEK1 -/- kat2J mice that we did observe to survive to two months of age, 50% (3/6) developed lymphomas and the other 50% (3/6) had lymphoid aggregates in various organs." (PMID 21214959, 2011). "We characterized the lymphoid tumors or lymphomas in NEK1 +/- mice by immunohistochemical analysis, using anti-CD3 antibodies for T-cells and anti-CD45R antibodies for B-cells." (PMID 21214959, 2011). "Genomic instability is also manifest in NEK1 +/- mice, which late in life develop lymphomas with a much higher incidence than wild type littermates." (PMID 21214959, 2011). "Consistently, 89% of mice heterozygous at the Kat2J locus (Nek1+/-) developed lymphomas between 17 and 24 months of age, compared to 30% of wild-type mice." (PMID 22040655, 2011).
short rib-polydactyly syndrome (3 papers, 2014 to 2020). Short rib-polydactyly syndromes are a group of bone malformations characterized by a narrow thorax and polydactyly (usually preaxial). "Mutations in NEK1 can cause Short-Rib Polydactyly Syndrome (Type Majewski), short-rib thoracic dystrophies, oral-facial-digital syndrome type II (Mohr syndrome), and, more recently, short-rib polydactyly syndrome (SRPS)." (PMID 32294979, 2020).
short-rib thoracic dysplasia (3 papers, 2017 to 2025). "We also introduced two pathogenic C21ORF2 mutants—L73P and L224P—found in ALS and Jeune syndrome, respectively, which show reduced association with NEK1." (PMID 37188479, 2023). "NEK1 mutations have also been found in other skeletal dysplasias such as Jeune syndrome and axial spondylometaphyseal dyplasia (SMD)." (PMID 37188479, 2023). "First, mutations in the C21ORF2 gene phenocopy NEK1 mutations in Jeune syndrome, SMD, and ALS; this pattern of similarity is unique, suggesting that the functions of these two genes are intimately linked." (PMID 37188479, 2023). "The R73P and L224P aa substitutions in C21ORF2 found in ALS and Jeune syndrome, respectively, might abolish interaction with NEK1." (PMID 37188479, 2023). "It is noteworthy that the pathogenic aa substitution L224P found in Jeune syndrome locates to the first of the two helices in the predicted interface, which may account for why this substitution weakens C21ORF2 association with NEK1." (PMID 37188479, 2023).
anaemia (2 papers, 2017 to 2023). "Sterility and anaemia are often associated with defects in DNA repair, and in this light, NEK1 has been implicated in homologous recombination (HR), a highly conserved pathway important for repairing double-strand breaks (DSB) in proliferating cells." (PMID 37188479, 2023). "NEK1-deficient mice show a range of defects beside kidney disease, including facial dysmorphism, dwarfism, cystic choroid plexus, male sterility, and anaemia." (PMID 37188479, 2023).
cervical cancer (2 papers, 2020 to 2022). A primary or metastatic malignant neoplasm involving the cervix. "To validate the findings regarding the prognostic role of Nek1, we finally analyzed data from a cervical cancer patient cohort derived from the TCGA databank." (PMID 32429458, 2020). "To independently confirm a Nek1 KD radiation sensitizing effect in a 6 h fractionation schedule, we next focused on cervical carcinomas for the following in vivo experiments and the analysis of clinical samples." (PMID 32429458, 2020). "Here, we report that Nek1 knockdown (KD) in combination with a 6 h fractionation regime resulted in radiation sensitization and growth delay in a xenograft model of cervical cancer suggesting that Nek1 might represent a valuable molecular target." (PMID 32429458, 2020). "In addition, we correlated Nek1 expression in biopsies of patients with cervical cancer with histopathological parameters and clinical follow-up." (PMID 32429458, 2020). "We also assessed Nek1 expression in patients treated with CRT and focused on histochemical analyses of patients with cervical cancer treated at a single center." (PMID 32429458, 2020). "We next investigated Nek1 expression in tumors of patients treated with CRT and focused our analyses on pretherapeutic samples from patients with cervical cancer treated at a single university center." (PMID 32429458, 2020).
dysplasia (2 papers, 2017 to 2025). A usually neoplastic transformation of the cell, associated with altered architectural tissue patterns. "For example, in short-rib thoracic dysplasia the G145R mutation would clearly cause the NEK1 kinase domain to be inactive, however it is unclear if the L253S mutation would have an effect on kinase activity as it is on a remote part of the C-terminal lobe of the kinase domain." (PMID 28710492, 2017).
glioblastoma (2 papers, 2020). The most malignant astrocytic tumor (WHO grade IV). "These include PCa stages according to Gleason score, head and neck squamous cell carcinoma, and glioblastoma, suggesting that this co-regulation is imparted by increased YAP1 stability when NEK1 is overexpressed or activated by TLK1, and not through transcriptional co-expression." (PMID 33297404, 2020).
motor neuron disease (2 papers, 2017 to 2025). "Here we assess a cohort of Scottish patients with differing NEK1 variants and resulting similarities and differences in clinical and pathological presentations of motor neuron disease." (PMID 38986433, 2025). "First, all patients exhibited neuropathology unrelated to motor neuron disease, i.e., aggregation of tau and amyloid, in addition to TDP‐43 (in all cases) and NEK1 aggregation (in Patient 2)." (PMID 38986433, 2025).
osteogenesis imperfecta (2 papers, 2023 to 2025). Osteogenesis imperfecta (OI) comprises a heterogeneous group of genetic disorders characterized by increased bone fragility, low bone mass, and susceptibility to bone fractures with variable severity. "In the case 2, 5 and 8, we found the WNT1or COL1A1-related VUS in osteogenesis imperfecta, and DYNC2H1 and NEK1-related asphyxiative hypoplasia of thorax." (PMID 37875969, 2023).
Renal cyst (2 papers, 2008 to 2014). A fluid filled sac in the kidney. "Aberrant ciliary signaling and cell cycle regulation are both implicated in the etiology of renal cysts and mutations in Nek1 are causal for kidney cyst formation." (PMID 18533026, 2008). "Late in life, kat2J heterozygous mice form renal cysts and the cells lining these cysts lack staining for Nek1." (PMID 25030234, 2014). "In the report, we examined the expression pattern of Nek1 and characterized the renal cysts that develop in kat2J mice." (PMID 25030234, 2014). "Late in life, kat2J/Nek1 +/− mice form renal cysts and the cells lining these cysts lack staining for Nek1." (PMID 25030234, 2014). "We report the expression pattern of Nek1 and characterize the renal cysts that develop in kat2J mice." (PMID 25030234, 2014). "Even with subsequent out-breeding to wild type C57Bl/6 J mice, we still found earlier development of renal cysts than previously reported in Nek1 −/− kat 2 J mice." (PMID 25030234, 2014). "Late in life, even kat2J/Nek1 +/− mice form renal cysts and the cells lining these cysts lack staining for Nek1." (PMID 25030234, 2014). "We show here for the first time that Nek1 +/− mice develop a mild form of cystic kidney disease late in life." (PMID 25030234, 2014). "Mammalian Nek1 is a candidate for this activity because renal cysts form in response to dysfunctional ciliary signalling." (PMID 18533026, 2008). "Most of the identifiable cilia in renal tubular cells observed by scanning electron microscopy in Nek1/kat2J −/− renal cysts (and in primary Nek1−/− tubular cells before propagation in culture) were relatively normal and uniform in appearance, although somewhat longer than expected." (PMID 25030234, 2014). "The expression of Nek1 increases after ischemia-reperfusion injury in tubular epithelial cells that aren’t cystic, but seems to be down-regulated or absent in renal tubular epithelial cells that line nascent renal cysts in Nek1/kat2J heterozygotes." (PMID 25030234, 2014).
retinal ciliopathy (2 papers, 2024 to 2025). "Previous studies have shown that CFAP410 is a component of a retinal ciliopathy-associated protein complex containing both NEK1 and SPATA7." (PMID 40018707, 2025). "Other studies also showed that CFAP410 is a component of a retinal ciliopathy-associated protein complex containing both NEK1 and SPATA7." (PMID 39255848, 2024). "Previous immunofluorescence studies showed that CFAP410 co-localizes with both the serine/threonine kinase NEK1 and a retinal ciliopathy protein called SPATA7 at the basal body in hTERT-RPE1 cells." (PMID 39255848, 2024).
thyroid tumor (2 papers, 2020). A benign or malignant neoplasm affecting the thyroid gland. "Concerning characteristics of the thyroid tumour, such as aggressiveness, NEK1 expression was higher in tumours with multifocality and in patients with lymph node metastasis." (PMID 31906878, 2020). "Once NEK1, NEK2, NEK3, and NEK5, all showed a higher level of expression in thyroid tumour tissue it was decided to expand the number of thyroid cases submitted to TMA analysis." (PMID 31906878, 2020).
Wilms tumor (2 papers, 2020 to 2025). An embryonal neoplasm characterized by the presence of epithelial, mesenchymal, and blastema components. "Chromosomal abnormalities in the NEK1 locus were found in Wilms tumour, the most common cancer of the kidney in infants and children." (PMID 31906878, 2020).
adenoma (1 paper, 2024). A neoplasm arising from the epithelium. "NEK1, in turn is predicted to be acted upon by HNF1A (p = 0.4), a TF involved synthesis of liver specific transcripts and whose absence predisposes to adenomas." (PMID 39102671, 2024).
adenovirus infection (1 paper, 2014). "First, we determined when Nek1 expression was significantly decreased after adenovirus infection." (PMID 24970796, 2014).
breast tumors (1 paper, 2025). "For instance, DelSIEVE inferred that gene NEK1 and NEK5, which had been reported to be related to breast tumors, experienced both a deletion and a mutation on the trunk, resulting in all sequenced cells having genotype 1/-." (PMID 40855447, 2025).
cervical tumor (1 paper, 2020). "Recent analyses indicate an involvement of Nek1 in the regulation of DNA damage repair by HR as shown for fibroblasts and HeLa cervical tumor cells." (PMID 32429458, 2020).
cholangiocarcinoma (1 paper, 2014). A carcinoma that arises from the intrahepatic biliary tree (intrahepatic cholangiocarcinoma) or from the junction, or adjacent to the junction, of the right and left hepatic ducts (hilar cholangiocarcinoma). "Furthermore, Nek1 is overexpressed in cholangiocarcinoma tumors and MCF7 cells." (PMID 25120679, 2014).
chronic lymphocytic leukemia (1 paper, 2019). "While no mutations of the NEK1 gene have been reported so far in MCL, they have been seen in Sezary Syndrome, chronic lymphocytic leukemia, and other hematopoietic malignancies." (PMID 31334109, 2019).
colorectal carcinoma (1 paper, 2020). A malignant epithelial neoplasm that arises from the colon or rectum and invades through the muscularis mucosa into the submucosa. "We focused on cervical and colorectal carcinomas as a proof of Nek1-mediated radiosensitization as both entities are among the most common cancers diagnosed in humans and cover important causes of mortality worldwide." (PMID 32429458, 2020). "Stably transduced doxycycline (Dox)-inducible Nek1 shRNA HeLa cervix and siRNA-transfected HCT-15 colorectal carcinoma cells were irradiated in vitro and 3D clonogenic radiation survival, residual DNA damage, cell cycle distribution, and apoptosis were analyzed." (PMID 32429458, 2020).
cyst (1 paper, 2014). A sac-like closed membranous structure that may be empty or contain fluid or amorphous material. "Since cyst-lining cells lose expression for Nek1, we suggest that stochastic inactivation of Nek1 is required for the manifestation of the PKD phenotype, as it is in humans and animals with heterozygous germ line mutations in PKD1 or PKD2 to manifest autosomal dominant PKD." (PMID 25030234, 2014). "As an important step in the characterization of how Nek1 may be involved in renal development and how its absence may lead to renal cystogenesis or cyst progression, we examined the expression pattern of Nek1 in normal, developing, and diseased mouse kidneys." (PMID 25030234, 2014).
dementia (1 paper, 2023). Loss of intellectual abilities interfering with an individual's social and occupational functions. "The research panel also identified three variants in NEK1, all in patients who did not report a family history of ALS, dementia or other neurological disease, all of whom had slow disease progression, as defined by survival of more than 5 years." (PMID 37159497, 2023).
Fanconi anemia (1 paper, 2017). Fanconi anemia (FA) is a hereditary DNA repair disorder characterized by progressive pancytopenia with bone marrow failure, variable congenital malformations and predisposition to develop hematological or solid tumors. "The partners of NEK1 found here are however not only involved in Homology DNA repair, but also in base excision, nucleotide excision, mismatch repair and the Fanconi Anemia pathway." (PMID 28710492, 2017).
female infertility (1 paper, 2017). Diminished or absent ability of a female to achieve conception. "Besides, differences observed in the phenotype, the lack of NEK1 ends up in male and female infertility." (PMID 28982183, 2017).
lung carcinoma (1 paper, 2022). "Results showed that there was overexpression of NEK2/4/6/8, low expression of NEK1/3/7, and no expression of NEK5/9/10/11 in lung cancer." (PMID 35105934, 2022).
lymphoid tumors (1 paper, 2011). "This lymphoid tumor phenotype demonstrates, in vivo, that haplo-insufficiency for NEK1 leads spontaneously to cancer." (PMID 21214959, 2011). "By 17-24 months of age, 30% of wild type mice (3/10) and 89% of NEK1 +/- kat2J littermate mice (33/36) developed lymphoid tumors." (PMID 21214959, 2011). "Interestingly, lymphoid tumor cells from older NEK1 +/- mice had distinct, polyploid DNA contents very similar to those seen in NEK1 -/- cells passed several times in culture." (PMID 21214959, 2011). "Most cells in lymphoid tumors from NEK1 +/- kat2J mice stained negatively for NEK1." (PMID 21214959, 2011).
medullary thyroid carcinoma (1 paper, 2020). "On the other hand, in the thyroid, the expression of NEK1 was increased in papillary and medullary carcinoma (p < 0.001, quantitative analysis)." (PMID 31906878, 2020). "In the broad spectrum TMA analysis (semiquantitative and quantitative), we observed an increased expression of NEK1, NEK2, NEK3, and NEK5 in papillary and medullary thyroid carcinoma." (PMID 31906878, 2020).
ovarian carcinoma (1 paper, 2026). A malignant neoplasm originating from the surface ovarian epithelium. "This study systematically investigates the oncogenic function and underlying mechanisms of NEK1 in ovarian cancer." (PMID 42193091, 2026). "Collectively, these findings establish NEK1 as a promising prognostic biomarker and therapeutic target, with potential utility in guiding genotoxic therapy strategies for ovarian cancer patients." (PMID 42193091, 2026).
pancreatic adenocarcinoma (1 paper, 2021). "To assess whether members of the NEK family (from NEK1 to NEK11) are associated with pancreatic cancer prognosis, we first compared their expression levels in tumors and normal tissue using pancreatic adenocarcinoma (PAAD) datasets from The Cancer Genome Atlas (TCGA) database." (PMID 34315872, 2021).